LEP (leptin)
Diseases named in the same sentence as LEP in open-access papers (continued):
Sharing a sentence is not in itself a finding about the gene and the disease.
Obesity (continued). "Hormonal imbalances in obesity are accompanied by elevated levels of leptin, resistin, visfatin, adipsin, and retinol-binding protein 4, among others." (PMID 41465437, 2025). "This is also complicated by the fact that diet-induced obesity in mice results in leptin resistance, recently suggested to be caused by chronic mTOR activation in POMC neurons that reduces leptin signaling." (PMID 40702736, 2025). "Although initially considered an anti-obesity signal, the current view is that leptin acts as a signal of energy deficit." (PMID 40702736, 2025). "Leptin, a hormone involved in regulating food intake and body weight homeostasis, is typically elevated in obesity, leading to a condition known as leptin resistance." (PMID 41256259, 2025). "Individuals with obesity had lower ghrelin, higher glycemia and higher leptin in comparison to controls." (PMID 40965347, 2025). "In the present work, we are reviewing literature to update the body of knowledge regarding the role of obesity and leptin in multiple sclerosis." (PMID 40019662, 2025). "Leptin plays a pivotal role in energy homeostasis, yet leptin resistance remains a major challenge in obesity treatment." (PMID 41016636, 2025). "Conversely, chronic inflammatory conditions resulting from metabolic, autoimmune, or infectious diseases can induce central leptin resistance, a recognized contributor to obesity." (PMID 40871683, 2025). "This study also makes brain Socs3 a potential therapeutic target for treating leptin resistance, type 2 diabetes and obesity." (PMID 40755762, 2025). "Numerous factors contribute to chronic inflammation in the context of obesity, with adipokines, particularly leptin, emerging as the connection between obesity and immunity." (PMID 40019662, 2025). "Leptin resistance disrupts the satiety and energy balance in the brain, contributing to increased adiposity and obesity." (PMID 41515969, 2025). "Accelerated brain activation in striatal–limbic regions responsible for emotion processing and reward—such as the amygdala—has been correlated with higher leptin levels in individuals with obesity." (PMID 40431402, 2025). "Contrary to the low leptin concentrations in our obese and light mares compared to control, leptin concentrations increase with the increase in the amount of body fat mass due to the presence of obesity-related leptin resistance." (PMID 40901060, 2025). "By interfering with adipose tissue physiology (increased leptin production) and hormone control (ghrelin secretion), oxidative stress exacerbates obesity and metabolic comorbidities." (PMID 40298778, 2025). "An example of these mutations is an alteration in leptin structure or leptin receptor (LEPR), leading to the inability of leptin to bind to its specific receptor and contributing to obesity via complex mechanisms that remain not fully understood." (PMID 40297673, 2025). "Increased body fat composition and high leptin occurrence are attributed to leptin resistance in obesity." (PMID 41295840, 2025). "Previous reports have indicated that celastrol exerts anti-obesity effects by enhancing leptin sensitization, decreasing food intake, and restoring glucose tolerance and insulin sensitivity." (PMID 40500724, 2025). "Naturally occurring mouse models of obesity have been instrumental in identifying the leptin-melanocortin system as a major regulatory pathway in energy homeostasis." (PMID 40702736, 2025). "Previous scientific research has proved increased expression of circulating adipokines, including leptin and apelin, in patients with obesity-related cancers such as breast cancer and prostate cancer." (PMID 40076482, 2025). "Several mechanisms have been proposed to drive glomerular hyperfiltration in obesity, including salt retention, activation of the renin–angiotensin–aldosterone and sympathetic nervous systems, and alterations in leptin signalling." (PMID 41282359, 2025).
Obesity (continued). "This is particularly relevant in patients with type 2 diabetes or obesity, where leptin dysfunction contributes to endothelial impairment and increased CV risk." (PMID 41463309, 2025). "This leptin resistance impairs appetite regulation and energy expenditure, further exacerbating obesity." (PMID 40095902, 2025). "Sex hormone estradiol modulates leptin sensitivity to control feeding and sexual dimorphism in diet-induced obesity via hypothalamic Cited1, while sex hormone receptors transcriptionally regulate sexually dimorphic gene expression." (PMID 40004248, 2025). "Clearly in contrast to classical leptin resistance in obesity, the metreleptin induced boost in leptin signalling was seemingly able to induce similar improvements as previously observed in patients with hypoleptinemia." (PMID 40616697, 2025). "Obesity and, by extension, dysregulated leptin signaling have been shown to alter NK cell numbers, phenotypes, and effector functions." (PMID 41516046, 2025). "Among these, leptin and resistin are the most extensively studied and are recognized as key signaling transducers linking obesity to psoriasis development." (PMID 40893809, 2025). "In clinical practice, deviations from the established leptin reference ranges can indicate the presence of metabolic disorders such as obesity, lipodystrophy, and eating disorders." (PMID 40152811, 2025). "Obesity results in significant changes in the adipokine profile, creating a shift toward elevated levels of pro-inflammatory adipokines, such as leptin and resistin, and reduced levels of anti-inflammatory adipokines, such as adiponectin." (PMID 41158939, 2025). "Chlorogenic acid demonstrated a potential anti‐obesity effect in high‐fat diet‐induced mice, where positive modulation of leptin and adiponectin was observed via PPAR‐alpha expression and increased beta‐oxidation of fatty acids." (PMID 40195898, 2025). "A slight decrease in plasma levels enhances leptin sensitivity, suggesting a potential new approach for obesity treatment." (PMID 40572503, 2025). "TNF-α levels are inversely correlated with insulin sensitivity, while IL-6 and IL-1β inhibit insulin receptor substrate 1 (IRS-1); moreover, elevated levels of leptin in women with pregestational obesity contribute to insulin resistance." (PMID 41374008, 2025). "Significant differences were observed in IL-6, IL-10, IL-13, 25-(OH) D3 levels, and leptin among children with asthma combined with obesity/overweight and those with asthma or obesity/overweight alone." (PMID 40083433, 2025). "Obesity is characterized by hyperleptinemia (elevated leptin levels) and leptin resistance, a state of reduced tissue sensitivity to leptin due to impaired signaling pathways." (PMID 40805060, 2025). "High-density lipoprotein cholesterol (HDL-C) plays a protective role against obesity by improving adipose tissue function, modulating the secretion of adipokines such as adiponectin and leptin, and exerting anti-inflammatory and antioxidant effects." (PMID 40376050, 2025). "In obesity, inflammatory cytokines stimulate leptin production, creating a vicious cycle of chronic inflammation." (PMID 40095687, 2025). "This study aimed to test patients with different clinical obesity phenotypes for duplications or deletions in key obesity-related genes and connect the results with the markers used to describe an obesity profile, like adiponectin, leptin, and insulin." (PMID 40429924, 2025). "It is worth noting that leptin and adiponectin, two adipokines known to be altered in obesity, activate AMPK in adipose tissue." (PMID 40825507, 2025). "It has recently been reported that even mild exercise, Yoga, a traditional mind–body practice that originated in ancient India, can modulate inflammation induced by obesity via regulating adipokines such as adiponectin and leptin." (PMID 40757778, 2025). "Elevated levels of leptin, resistin, MCP-1, and ENA-78 are associated with various aspects of obesity-related complications." (PMID 39962072, 2025).
Obesity (continued). "Leptin resistance, commonly observed in individuals with obesity, is a relevant condition characterized by decreased responsiveness to leptin, even at high concentrations, leading to hyperleptinemia." (PMID 40787788, 2025). "Pancreastatin has been shown to impair glucose-stimulated insulin secretion and induce insulin resistance, whereas catestatin appears to exert anti-obesity effects by enhancing lipid mobilization and leptin signaling." (PMID 41480370, 2025). "The concentration of leptin in peripheral blood increased during obesity and GDM, while adipokine concentration decreased in obese and GDM samples." (PMID 41302116, 2025). "Leptin, the first fat factor discovered, exists in particularly high levels in the blood of patients with obesity and myocardial infarction." (PMID 40417460, 2025). "Persistent activation in obesity leads to a disruption in leptin signaling and an increase in central inflammation." (PMID 41515969, 2025). "In obesity, decreased sensitivity to leptin (LEP), a key adiponectin involved in energy balance and hunger inhibition, often leads to leptin resistance, decreased satiety and increased body mass." (PMID 39375979, 2025). "In obesity, adipocytes exhibit upregulated expression of pro-inflammatory adipokines, such as leptin and resistin." (PMID 40893809, 2025). "Other studies have observed a link between adiponectin and leptin from adipocytes in obesity and reflux, which is thought to be from the dysregulation of the levels of these proteins in obesity." (PMID 40272754, 2025). "In this context, with a focus on obesity as a potential risk factor for multiple sclerosis (MS), the objective of this article is to comprehensively review the literature pertaining to the roles of obesity and leptin in the development of MS." (PMID 40019662, 2025). "Elevated leptin levels and reduced adiponectin levels result from adipose tissue dysfunction in obesity." (PMID 40584451, 2025). "Leptin resistance is characterised by increased appetite and less consumption of energy, leading to the development of obesity and cardiovascular disease." (PMID 40045164, 2025). "A study in Italy that screened 209 patients with obesity for mutations in the MC4R, LEP, and LEPR genes identified only one novel pathogenic frameshift variant in the MC4R gene, which disrupted gene signaling." (PMID 40149731, 2025). "Obesity enhances leptin resistance that precipitates limitations in the effects of leptin; therefore, a far greater amount of leptin is required to induce the feeling of satiety." (PMID 40564637, 2025). "The Christensenellaceae has been reported to regulate liver lipid metabolism by inhibiting fat synthesis, preventing obesity, and modulating key antiaging indicators such as blood glucose and leptin." (PMID 40469513, 2025). "In this mouse strain, impaired leptin signalling in the hypothalamus leads to hyperphagia and obesity accompanied by elevated levels of insulin and leptin, hyperglycaemia, and the development of insulin resistance." (PMID 40149720, 2025). "The levels of sOB-R vary depending on the metabolic condition, including disorders like type 1 diabetes mellitus and obesity, which can lead to either increased or decreased leptin sensitivity." (PMID 41441006, 2025). "Obesity has been found to cause localized decreases in PO2, resulting in elevated levels of leptin, IL-6, vascular endothelial growth factor (VEGF), glucose transporter 1 (GLUT1), and PAI-1." (PMID 40871683, 2025). "Insulin resistance and related disorders, such as obesity and NAFLD, have been linked to adiponectin and leptin." (PMID 41347218, 2025). "Elevated leptin levels in boys with obesity were shown to prematurely activate the HPG axis, leading to earlier gonadarche and other pubertal milestones." (PMID 39941454, 2025).
Obesity (continued). "In obesity, hypertrophic adipocytes release a spectrum of pro-inflammatory adipokines (e.g., leptin and resistin) and cytokines (e.g., IL-1β and IL-6), which are known to exacerbate autoimmune conditions." (PMID 40900762, 2025). "In conclusion, there were significant differences in IL-6, IL-10, IL-13, 25-(OH) D3 levels, and leptin levels among children with asthma combined with obesity/overweight and those with asthma or obesity/overweight alone." (PMID 40083433, 2025). "In obesity, chronic inflammation and adipokine dysregulation (e.g., leptin resistance) induce pancreatic β-cell iron overload through hepcidin-mediated ferroportin (FPN) suppression." (PMID 40689204, 2025). "Obesity is recognized as a PDAC risk factor; therefore, leptin is expected to have a role in this cancer’s development." (PMID 40940878, 2025). "In obesity, leptin—a hormone responsible for regulating satiety and energy balance—is chronically overproduced, leading to leptin resistance." (PMID 40001516, 2025). "Secondly, obesity-related inflammation can lead to leptin resistance and decreased adiponectin secretion, and induce cerebral neurodegeneration and neurodegenerative diseases." (PMID 40740373, 2025). "In the obesity and diabetes groups, insulin resistance and hyperinsulinemia were observed despite high leptin levels." (PMID 40095937, 2025). "In the context of obesity, it has been demonstrated that leptin increases the release of EVs by epithelial mammary carcinoma cells." (PMID 40523654, 2025). "Recent studies have revealed that knocking out the LEPR or leptin coding gene in mice leads to insulin resistance, hyperphagia, and obesity." (PMID 39812542, 2025). "This study underscores the importance of EVs in the obesity-cancer link and offers new insights for therapeutic strategies targeting leptin signaling and EV-mediated communication in breast cancer." (PMID 40485730, 2025). "For example, elevated adipsin and leptin levels have been correlated with more marked clinical activity in RA patients, especially in those with coexisting conditions such as obesity and periodontal infections." (PMID 40842998, 2025). "Since obesity reduces adiponectin and increases leptin beyond physiological levels, the positive effects of these adipokines are replaced by detrimental effects, such as the reduction in most sperm quality parameters." (PMID 40002337, 2025). "Elevated leptin levels, proportional to body fat stores, are commonly observed in individuals with obesity." (PMID 39857920, 2025). "In animals, circulating leptin levels are proportional to body fat mass, with increasing obesity leading to increased leptin concentrations." (PMID 40522819, 2025). "In the present study, the decreased concentrations of adiponectin and high levels of leptin in the obesity and diabetes groups seem to downregulate the cardiometabolic effects of the former." (PMID 40095937, 2025). "Compared to all normal-weight and metabolically healthy individuals, leptin levels were higher among those with obesity and/or metabolically unhealthy status, with a larger effect observed in obesity." (PMID 40362681, 2025). "We discovered two adult sisters in Colombia, lineally consanguineous, with severe obesity and undetectable serum leptin levels despite markedly elevated body fat." (PMID 40415699, 2025). "They reported that leptin gene level overexpression was found in the adipose tissue of individuals with obesity and had a strong positive correlation with body fat percentage." (PMID 39837875, 2025). "Socs3 is upregulated in obesity and inhibits leptin and insulin signaling, while its downregulation reduces hepatic lipid levels in obese Sprague–Dawley rats." (PMID 40535017, 2025). "Combined parental obesity/high-fat and high-sugar diet augments single-parent obesity effects on hypothalamus inflammation, leptin signaling, and obesity in adult mice and rat offspring." (PMID 40722883, 2025).
Obesity (continued). "An enhanced comprehension of the genetic and molecular foundations of obesity has underscored the pivotal function of the leptin–melanocortin pathway in governing appetite, energy expenditure, and sustained body weight equilibrium." (PMID 41226372, 2025). "PTP1B impairs hypothalamic insulin and leptin signaling and is upregulated in obesity, where it contributes to central insulin resistance." (PMID 40699839, 2025). "Understanding this interplay between insulin, leptin, obesity and thyroid hormones highlights the importance of managing both obesity and thyroid function to break the cycle of metabolic and endocrine disruptions." (PMID 39857741, 2025). "Particularly, disruption of the 5-hydroxytryptamine 2C (5-HT2C) receptor pathway has been reported to induce leptin-independent hyperphagia, thereby exacerbating both obesity and insulin resistance." (PMID 41226484, 2025). "In an obesity model, anthocyanins were able to reduce body mass and adipose tissue mass, positively impacting the secretion of the adipokines leptin and resistin, corroborating the improvement of inflammation by modulating the TLR4/AMPK pathways." (PMID 40195898, 2025). "Obesity contributes to heightened PD-1 expression and increased release of PD-1 protein from T cells, along with elevated secretion of adiponectin and leptin from adipose tissue." (PMID 40013137, 2025). "Mechanistically, exposure to air pollution and obesity are believed to have similar effects on the body, including systemic inflammation and disruptions in metabolic hormone signaling, such as leptin resistance and altered glucose metabolism." (PMID 41515969, 2025). "Due to the intricate link with leptin actions, the central melanocortin system has been recognized as a useful drug target to combat obesity and other leptin-resistant related disorders." (PMID 41016636, 2025). "Conversely to adiponectin, leptin concentrations were higher in participants with obesity, and diabetes, as compared to control group; diabetics with obesity showed the highest means values." (PMID 40095937, 2025). "Probiotics have demonstrated potential in modulating levels of HDL-C, LDL-C, lipocalin, leptin, and TNF-α in overweight or obese children, potentially alleviating metabolic symptoms associated with obesity." (PMID 40242164, 2025). "Leptin levels are elevated in patients with obesity and, after the stimulation of tumoral cells with this hormone, IL36G levels significantly increased (P < 0.05)." (PMID 40268791, 2025). "Increased leptin levels observed in obesity are thought to play a role in the premature activation of the GnRH pulse generator, which leads to the early onset of pubertal signs." (PMID 40095159, 2025). "In obesity, the growth-promoting effects of leptin on VSMC lead to vascular remodeling, triggering atherosclerotic disease progression." (PMID 40940776, 2025). "The endocrine disruption extends beyond estrogen production alone, as the expanded adipose tissue in obesity also alters the secretion of adipokines such as leptin and adiponectin." (PMID 41301707, 2025). "The strong correlations between these proteins and visceral adiposity, elevated leptin, and impaired vascular function reinforce the link between adiposome cargo and systemic metabolic and vascular disturbances in obesity." (PMID 40981199, 2025). "Some of these GPCRs have been investigated as potential targets for obesity treatment and demonstrate physiological interaction with leptin signaling." (PMID 41016636, 2025). "Conversely, leptin blockade or LepR antagonism in obesity or autoimmunity can rebalance the activity of effector/regulatory T cells, reduce pathogenic cytokine production, and enhance immune regulation." (PMID 41516046, 2025). "Aerobic exercise training effectively mitigated some of the obesity‐induced changes in the tPVAT, partially restoring the anti‐contractile response to 5‐HT and reducing circulatory leptin, TNF‐α, and malondialdehyde." (PMID 40842420, 2025).